CDKN1A (cyclin dependent kinase inhibitor 1A)
Diseases named in the same sentence as CDKN1A in open-access papers (continued):
Sharing a sentence is not in itself a finding about the gene and the disease.
diabetes (15 papers, 2011 to 2025). "Diabetes increased kidney expression of genes associated with injury (Kim1, ten-fold), senescence (Cdkn1a, Cdkn2a, 10 to 18-fold) and fibrosis (Tgfb1, Ctgf, Pai1, Timp1, Col1α1, Col4α1 and Fn1, two- to six-fold)." (PMID 41332229, 2025). "A maternal high-fat diet or diabetes (via streptozotocin treatment) is additionally associated with increased expression of the cell cycle inhibitor, cyclin dependent kinase inhibitor 1A (Cdkn1), and a reduction in the developmental gene, Wnt1 in the liver of exposed offspring." (PMID 32494846, 2020). "Senescence in TECs was identified by nuclear staining of Cdkn1a, which was extremely rare in normal mouse kidneys, but was a significant feature in the cortex of mouse kidneys after development of diabetes, which was further increased by IRI." (PMID 38391050, 2024). "The gene most robustly induced in both forms of diabetes was Cdkn1a, also known as p21." (PMID 21533091, 2011). "Cdkn1a was induced over 20-fold in Akita mice though only about 4-fold in db/db mice, consistent with the generally more robust effect of diabetes on gene expression in Akita mice compared to db/db mice, though interestingly albuminuria was greater in db/db mice than in Akita mice." (PMID 21533091, 2011). "Prominent genes were RHOA, AKT1, RAC1, MDM2, CDKN1A, and VEGFA, which play important roles in TGF-beta and mTOR signaling (KEGG database), signaling by Wnt and by NOTCH (Reactome database), and in complications in diabetes mellitus (DisGeNET database)." (PMID 35742976, 2022).
liver cancer (15 papers, 2017 to 2025). An epithelial or non-epithelial malignant neoplasm that arises from the liver. "CDKN1A can be considered as an independent factor for the development of liver cancer, and in patients with cirrhosis, high expression of CDKN1A may be associated with the occurrence of liver cancer." (PMID 34095224, 2021). "With bioinformatics analysis, it can be inferred that panobinostat inhibits liver cancer growth by suppressing the cell cycle pathway and downregulating CDKN1A, which aligns with reported literature." (PMID 38994794, 2024). "To further investigate the mRNA regulatory relationship between TRIM71 and CDKN1A in normal liver and liver cancer, we analyzed m6A-RIP seq of HuH-7 cells and found CDKN1A mRNA has no significant m6A modification." (PMID 39267787, 2024). "CDKN1A is another protein that protects against many cancers including liver cancer." (PMID 36765862, 2023). "Our findings on mouse models of liver cancer, and data from human liver cancer patients, show that SOCS1 suppresses the expression of CDKN1A, and in doing so, prevents the ability of liver cells to withstand the stress associated with cancer growth." (PMID 36765862, 2023). "In human liver cancer, miR-93-5p directly promoted cells proliferation by targeting PTEN and cyclin-dependent kinase inhibitor p21 (CDKN1A)." (PMID 29361788, 2018). "The E2F1 gene was moderately expressed in normal liver tissue and highly expressed in liver cancer tissue; The CDKN1A and CDK6 were not expressed in liver cancer tissues or normal liver tissues." (PMID 36699068, 2022). "NUPR1 expression is known to be upregulated after anticancer drug treatment (doxorubicin, gemcitabine, paclitaxel, celecoxib, and sorafenib) in breast and liver cancer cells, resulting in the downstream activation of the PI3K/AKT signaling pathway and CDKN1A/p21 phosphorylation." (PMID 33801927, 2021).
sarcoma (15 papers, 2001 to 2025). A usually aggressive malignant neoplasm of the soft tissue or bone. "Consistent with the mRNA evaluation, protein levels of Cdkn1a and Mdm2 were also detectably upregulated in the two W/+ sarcoma cell lines treated with ATO, in a dose-dependent manner." (PMID 38030599, 2023). "Consistently, Cdkn1a and Ink4a, as well as Il-6, were upregulated in Ebf1-KRAB-expressing sarcoma cells when compared with control NANOG-KRAB-expressing sarcoma cells." (PMID 31488818, 2019).
liver disease (12 papers, 2010 to 2025). "Similar to in Bcs1lp.S78G;mt-Cyb p.D254N mice, AOX also prevented the hepatic induction of γH2AX and CDKN1A, and attenuated the liver disease in the juvenile (P35) Bcs1lp.S78G mice." (PMID 37095097, 2023). "CD81(CD81 Molecule) and CDKN1A (Cyclin Dependent Kinase Inhibitor 1A), the potential target genes of hsa-miR-3180, were located in liver diseases pathways." (PMID 37051592, 2023). "The gene product of CDKN1a (which was up-regulated with a 1.78 fold change) (p = 0.032) in expression in high- compared to low-risk PBC, p21WAF1/Cip, is a marker of biliary senescence and has been shown to predict outcome in a number of liver diseases and to correlate with Scheuer stage." (PMID 27913155, 2016). "Overall, the upregulation of CDKN1A, NFKB2, RELB, and PDIA3 indicates a worse prognosis of liver disease and an impaired immune response against HIV." (PMID 33785040, 2021).
endometrial cancer (11 papers, 2017 to 2025). Primary or metastatic malignant neoplasm involving the endometrium (mucous membrane that lines the endometrial cavity). "More importantly, DETA/NO and progesterone-inhibited invasion of endometrial cancer by upregulating CDKN1A expression in vitro." (PMID 35847989, 2022). "Some reports indicated that the growth of endometrial cancer cells was hampered when CDKN1A was upregulated, which implied that p21 inhibited the proliferation of endometrial cancer." (PMID 35847989, 2022). "The high expressions of CDKN1A, SLC7A11, and SAT1 were found to be linked to the low stage, grade of pTNM, and longer survival time in endometrial cancer." (PMID 35847989, 2022). "The Journal retracts the article titled “Nitric Oxide Donor DETA/NO Inhibits the Growth of Endometrial Cancer Cells by Upregulating the Expression of RASSF1 and CDKN1A”, cited above." (PMID 41217138, 2025). "Among them, we identified four genes (SFN, CDKN1A, GADD45G, and TP73) whose expression was positively correlated with endometrial cancer from TCGA data." (PMID 36358786, 2022). "In Ishikawa endometrial cancer cells, MTF treatment upregulated cyclin dependent kinase inhibitor 1A (CDKN1A; alias, p21), resulting in comparably more cells arresting in the G1 and G2/M phases." (PMID 30241339, 2018). "Our data thus suggest that these correlations between SESN2 and cell cycle-associated genes are independent of the role of CDKN1A and CDKN1B as tumor suppressors in the tumor of patients with endometrial cancer." (PMID 32899752, 2020).
multiple myeloma (11 papers, 2013 to 2026). "In myeloma cells, the expression of CDKN1A and apoptotic genes is induced, which leads to cell cycle arrest and apoptosis." (PMID 24927749, 2014).
acute myeloid leukemia (10 papers, 2017 to 2025). Acute myeloid leukemia (AML) is a group of neoplasms arising from precursor cells committed to the myeloid cell-line differentiation. "In a mouse model of acute myeloid leukemia, qPCR analysis of bone marrow cells revealed elevated expression of aging markers Cdkn2a, Cdkn1a, and SASP factors, while the expression of Lmnb1 was reduced." (PMID 39963130, 2025). "In our previous studies, we demonstrated that isoflavonoid 8-hydroxydaidzein induced apoptosis by downregulating acute myeloid leukemia (AML)-associated genes such as RUNX1, CCND2, and MYC in U937 cells while upregulating CDKN1A (p21) and suppressing BCL2 expression in K562 cells." (PMID 40508126, 2025). "In acute myeloid leukemia (AML), the expression of CDKN1A/p21 is significantly reduced in refractory patients, indicating a poor prognosis." (PMID 41040512, 2025). "Recently, a cell-line based experiment indicates that knockdown of PIP4K2A in acute myeloid leukemia (AML) results in accumulation of the cyclin-dependent kinase inhibitors (i.e., CDKN1A and CDKN1B), G1 cell cycle arrest and apoptosis." (PMID 30697230, 2018).
esophageal cancer (10 papers, 1999 to 2023). A primary or metastatic malignant neoplasm involving the esophagus. "Studies have demonstrated CDKN1A overexpression to be associated with poor prognosis in gastric and esophageal carcinomas." (PMID 29342159, 2018). "As for other cancers, such as prostate or esophageal carcinomas, MSI1 depletion was associated with an arrest in the G1 phase accompanied by a de–regulation of CDKN1A (p21/WAF) and NUMB." (PMID 34062997, 2021). "Several studies have indicated that the CDKN1A overexpression is correlated with poor prognosis in different cancers, including esophageal carcinoma." (PMID 28258440, 2017).
heart failure (10 papers, 2017 to 2026). Inability of the heart to pump blood at an adequate rate to meet tissue metabolic requirements. "Recent studies have linked alterations in CDKN1A expression to cardiac hypertrophy and heart failure." (PMID 39069811, 2025). "Individual genes driving these enrichments included Cdkn1a, a known regulator of cardiomyocyte cell cycle implicated in heart failure, which increased in significance (Padj = 6.04e-03 to 4.7e-06)." (PMID 40705823, 2025). "The GWAS of NT-proBNP levels identified cardiomyopathy- or heart failure-associated genetic loci (eg, HSPB7/CLCNKA, CDKN1A, TTN, FLNC, and BAG3)." (PMID 41054850, 2025). "CDKN1A was identified an important gene which also significantly decrease in patients suffered heart failure." (PMID 35419165, 2022). "Studies have shown that CDKN1A expression is increased in human heart failure and may be involved in human coronary disease and HCM." (PMID 40609041, 2025). "Hypertension and heart failure correlated with all proteins, except NOTCH1 and CDKN1A, respectively." (PMID 41054850, 2025).
brain tumor (9 papers, 1995 to 2025). "However, the detailed roles of CDKN1A in human brain tumors, especially GBM, have rarely been studied." (PMID 33621203, 2021). "On the molecular level, all three cell cycle arrest genes that were upregulated under combination therapy in our study (GADD45A, CDKN1A, and BTG2), where Cx43 function was inhibited, showed a positive correlation with GJA1 levels in brain tumor tissue." (PMID 39680504, 2025). "Strikingly, CDKN1A expression is five-and four-fold lower in T-ALL compared to B-ALL and brain tumors, respectively." (PMID 35401501, 2022). "Supporting this hypothesis, CDKN1A gene expression levels in the PCGP cohort is on average six- to seven-fold lower in pediatric T-ALL compared to B-ALL, AML or brain tumors." (PMID 35401501, 2022).
atherosclerosis (8 papers, 2014 to 2025). A disease characterized by the build-up of fatty material and calcium deposition in the arterial wall resulting in partial or complete occlusion of the arterial lumen. "CDKN1A, a regulator of ischemia–reperfusion injury, is associated with atherosclerosis and risk of myocardial infarction progression." (PMID 38360841, 2024). "CDKN1a/p21, as an ischemia-reperfusion injury modulator, was associated with the risk of atherosclerosis and MI progression." (PMID 35845045, 2022). "Cyclin-dependent kinase inhibitor CDKN1A is involved in inducing cellular senescence in MØ, contributing to atherosclerosis progression by releasing pro-inflammatory factors." (PMID 40607379, 2025). "Inhibition of SYK or CDKN1A might prevent against atherosclerosis development." (PMID 25333956, 2014).
breast tumor (8 papers, 2004 to 2024). "Elevated CDKN1A expression was also detected in BRCA2-mutated breast tumours relative to those carrying wild type BRCA2 gene (TCGA data)." (PMID 34389725, 2021). "The regulation of CDKN1A gene expression by LRH-1 influences the proliferation of breast tumor cells." (PMID 38418940, 2024).
cardiac hypertrophy (8 papers, 2020 to 2025). "In a pressure overload-induced cardiac remodeling paradigm, cdkn1a knockdown mice showed reduced myocardial hypertrophy and fibrosis and improved cardiac function when compared to wild type mice." (PMID 36704356, 2022). "Moreover, a recent study reported that CDKN1A participates in the pathogenesis of diabetic glomerular hypertrophy." (PMID 34338139, 2021). "Among them, those coding for DUSP family members, CDKN1A, BTG2, GADD45B,34, and MCL-1 have been previously shown to be upregulated in human myocardial tissues in response to stress and/or DNA damage and to play a role in the regulation of cardiac hypertrophy and remodeling in animal models." (PMID 31924244, 2020).
diabetic nephropathy (8 papers, 2013 to 2024). "CDKN1A was also found to prevent renal interstitial fibrosis in diabetic nephropathy by inhibiting the expression of miR-93-5p." (PMID 34338139, 2021).
Insulin resistance (8 papers, 2017 to 2025). Increased resistance towards insulin, that is, diminished effectiveness of insulin in reducing blood glucose levels. "J 2 (JAG2), NOTCH3, CDKN1A, HES1, and MAPT are novel biomarkers for the development of insulin resistance." (PMID 30678306, 2019). "Recently, miR-93 has been introduced to be a critical player in insulin resistance and proliferative status of GCs in PCOS via targeting GLUT4 in adipose tissue and CDKN1A in GCs, respectively." (PMID 29116087, 2017).
renal cell carcinoma (8 papers, 1999 to 2024). "p21Cdkn1a mediates G1 arrest by inhibiting CDK1 and CDK2 and loss of CDKN1A is a predictor of poor outcome in renal cell carcinoma." (PMID 35401501, 2022). "For example, we recently showed that elevated expression of CDKN1a (p21) confers chemoresistance to renal cell carcinomas, which share common hypoxia-induced, pro-angiogenic signatures with vascular tumors." (PMID 21062482, 2010). "Several researchers pointed out that lncRNA SNHG16 could promote renal cell carcinoma migration and invasion by suppressing the CDKN1A." (PMID 36611858, 2022).
thyroid cancer (8 papers, 1996 to 2024). "The combination of hsa-miR-4732-5p and hsa-miR-1180-3p as an input for pathway analysis provided “thyroid cancer” as an altered pathway (P = 0.037), including MAP2K2, CDKN1A, and TRP as target genes." (PMID 36583003, 2022).
viral infection (8 papers, 2018 to 2025). "With the addition of CDKN1A to our model, we have accounted for the activities of a critical cell cycle regulator allowing for future model expansion to include of cellular stress pathways associated with dysregulations in cancer and viral infection." (PMID 32251461, 2020). "IFN-stimulated genes (ISGs), including CRP, IFIT1, LRG1, SLC1A1, and CDKN1A, were upregulated during HBoV1 infection, suggesting that viral infection elicited an antiviral response from the host cell." (PMID 39846742, 2025). "Further, the lentivirus‐mediated overexpression of CDKN1A notably reduced the M1 virus infection and titer." (PMID 33037696, 2020). "Transcriptome analysis revealed that the inhibition of RAS signaling upregulates the type I interferon antiviral response, and further RNA interference screen identified CDKN1A as a key downstream factor that inhibits viral infection." (PMID 33037696, 2020). "Interestingly, MSC are usually resistant to viral infection due to their expression of interferon (IFN) stimulated genes (ISG) such as IFITM (interferon-induced transmembrane family), IFI6, ISG15, SAT1, PMAIP1, p21/CDKN1A, and CCL2 that preempt viral infection." (PMID 32766251, 2020).
adenoma (7 papers, 1996 to 2025). A neoplasm arising from the epithelium. "Consistent with its previously reported repression by AP42, Cdkn1a/p21 was upregulated in Ap4-deficient adenomas." (PMID 30177706, 2018). "CDKN1A expression was significantly higher in adenomas compared to adenocarcinomas (mean: 1.785 vs. 1.637, p = 0.041)." (PMID 40699620, 2025). "In the paired analysis, 61% of patients exhibited higher CDKN1A expression in adenomas than in their matched adenocarcinomas (p = 0.022)." (PMID 40699620, 2025). "Moreover, a comprehensive transcriptomic analysis of senescent fibroblasts found strong involvement of CDKN1A (p21Cip1) in maintaining the senescent state, a pattern that aligns closely with our results that CDKN1A exhibited higher expression in adenomas." (PMID 40699620, 2025). "CDK1 was identified as expressed in adenomas and CRC, while expression of its partner CDKN1A was absent, suggesting that the proliferative activity of CRC, which may be an early event in carcinogenesis, is not solely dependent on control of the cell cycle by these two genes." (PMID 36362041, 2022).